CD4 (CD4 molecule)
Diseases named in the same sentence as CD4 in open-access papers (continued):
Sharing a sentence is not in itself a finding about the gene and the disease.
tumor (continued). "In spite of the limited numbers of such studies investigating CD4 T cell based immunotherapy in cancer patients, it is becoming apparent that Th1 cells possess the capacity to modulate the immune response and potentially enhance tumor immunity in the clinical setting." (PMID 23533029, 2013). "Thus, we used flow cytometry to measure changes to tumor-infiltrating CD4+ and CD8+ T cells." (PMID 24013775, 2013). "Thus, analyzing for HLA-DR expression of the primary tumor and metastasis and subsequent adoptive CD4+ T-cell transfer might be a promising approach for future immunotherapy." (PMID 22890822, 2013). "Moreover, CD4 T cell and NK cells were found to work synergistically towards tumor removal." (PMID 23800124, 2013). "Extrapolating from this, it is tempting to conclude that majority of tumor-Treg cells are likely nTregs based on their Foxp3 stability and not iTregs as Foxp3 unstable Treg cells would otherwise constitute a sizable fraction of tumor-Tregs if they were induced from conventional CD4+ T cells." (PMID 23874336, 2013). "Therefore, different tissue contexts may determine whether Tim-3+ CD4 T cells exert a beneficial or detrimental effect on tumor immunopathogenesis." (PMID 23526963, 2013). "Although these results strongly implicate a tumor-suppressive role of B7-H3, the exact physiological and pathological role of B7-H3 remains elusive, since B7-H3 has also been shown to stimulate proliferation and cytokine production of both CD4+ and CD8+ T-cells." (PMID 23940627, 2013). "Of the two tumor-specific T lymphocyte subsets, CD8+ cytotoxic T lymphocytes (CTL) recognize tumor-associated antigen (TAA)-derived peptides in the context of MHC class I molecules (MHC-I), whereas CD4+ helper T (Th) cells respond to peptide-MHC class II (MHC-II) complexes." (PMID 24386437, 2013). "Interestingly, treatment with viruses positive for three MHC class II-restricted antigens, i.e., neuroblastoma RAS, TRP1, and cytochrome c1, resulted in complete anti-tumor responses that were accompanied by significant CD4 T helper cell type 17 (Th17) responses." (PMID 24265631, 2013). "Interestingly, this effect was quite dramatic in tumor tissue, for both CD4 and CD8 T cells." (PMID 23557194, 2013). "Importantly, we demonstrate that in vivo depletion of regulatory T cells (Tregs) and CD8+ T cells in FBL-3-bearing DEREG transgenic mice augments IL-2 and GzmB production by CD4+ T cells and increases FV-specific CD4+ T-cell effector and cytotoxic responses leading to the complete tumor regression." (PMID 22890822, 2013). "We show that by acting via endogenous CD40L and IL-2, and acquired peptide-MHC-I (pMHC-I) complex signaling, CD4+ Th cells enhance survival of transferred effector CTLs and their differentiation into the functional memory CTLs capable of protecting against highly-metastasizing tumor challenge." (PMID 23785406, 2013). "In addition, a sample of the tumor digest was analyzed by flow cytometry prior to culture, which revealed that 41.1% of CD4+ T cells within the tumor had a Treg phenotype, representing an approximate 10-fold enrichment over frequencies in the blood (not shown)." (PMID 23110239, 2012). "Mounting evidence suggests that in addition to thermal ablation of cancer cells, HIFU may also boost the host antitumor immune response including CD4+/CD8+ related tumor-infiltrating lymphocytes (TILs), dendritic cells (DCs), and antigen presenting cells (APCs)." (PMID 23140567, 2012). "Interestingly, both CD8+ as well as CD4+ T cells are essential for therapeutic effectiveness suggesting that CD4+ T helper cells contribute to the tumor destruction either directly or indirectly e.g. by promoting T-cell activation via cross-talk with accessory immune cells." (PMID 23134699, 2012).
tumor (continued). "Immunoregulatory cytokines such as IL-10 and TGF-β play an important role in immune tolerance, and it seems that suppressor effect of regulatory T cells (CD4+CD25+) on the development of tumor associated antigen-reactive lymphocytes is independent of cytokines." (PMID 22927872, 2012). "Tumor infiltrating lymphocytes (TIL) CD3+, CD4+, CD8+, and GrB+ were predominantly observed within the cancer stroma, especially in the papillary-axis, underlying stroma, and lymphoid aggregates, and only rarely as individual cells within the epithelial part of the tumor." (PMID 23275325, 2012). "However, the nature of TIM-3+CD4+ T cells in the tumor microenvironment is unclear." (PMID 22363469, 2012). "Indeed, among the various sub-populations of anti-tumour CD4+ T cells, CD4 Th1 cells are of particular interest through their ability to enhance the function of antigen presenting cells and to target the tumour stroma and angiogenesis through the secretion of TNF-α and IFN-γ." (PMID 23284752, 2012). "Therefore, focussing on strategies to generate better and suitable MHC class II–restricted activation of tumor specific CD4+ T helper cells may have an important impact on fighting and defeating cancer." (PMID 22849661, 2012). "However, the role of PD1 in regulating CD4+ T-cell response in the tumor context is less clear." (PMID 22400040, 2012). "Interestingly, mice rejecting CIITA-tumors and mice vaccinated with CIITA-tumor cells rejecting a challenge with parental tumors displayed a polarized CD4+ TH1 cell phenotype in their tumor-draining lymph nodes, as compared to TH2-like cells found in parental tumor-bearing mice." (PMID 22849661, 2012). "And third, cotreatment with MC2 TCR-transduced CD8 and MA3 TCR CD4 T cells may be of particular interest to boost antitumor immunity and counteract selected growth of epitope-negative tumor variants." (PMID 22400038, 2012). "However TCR transgenic SH2D2A-deficient peripheral CD4+ T cells in tumor mice displayed higher CD69 surface expression compared to mice without tumor (p = 0.05) or unchallenged mice (p<0,007)." (PMID 23144743, 2012). "Interestingly, we found that transfer of female CD4 T cells mediated similar tumor control when transferred with CD8 T cells of either male or female origin, while male CD4 T cells were unable to mediate tumor control even when infused simultaneously with female CD8 T cells." (PMID 22493742, 2012). "A fundamental requisite for clinical efficacy of anti-viral and anti-tumor vaccines is the induction/expansion of Ag-specific CD4+ T cells; therefore, pre- and post- vaccination immune monitoring should evaluate and compare the presence, frequency, phenotype and function of Ag-specific CD4+ T cells." (PMID 22879946, 2012). "Importantly, the most dramatic effect was seen in the tumor microenvironment as the absolute number of OT-II CD4+FoxP3.gfp+ T cells, assessed by flow cytometry or confocal microscopy, were reduced in mice treated with SA-4-1BBL as compared with SA treated controls." (PMID 22870329, 2012). "Moreover, the specific induction of CD4+ T cells has been suggested to lead to tumor eradication by delayed type hypersensitivity responses and recently cancer patients have been cured after adoptive transfer of CD4+ T cells with tumor reactivity." (PMID 23189185, 2012). "Furthermore, repeated administration of EJHE or EJHE-WR may resulted in an increase in tumor-infiltrating CD4+CD25+Foxp3+ Treg cells that led to increase in TGF-β in tumor microenvironment." (PMID 21294856, 2011). "Interestingly, the observed expansion of naïve CD4+CD127lowFOXP3+ Treg cells was also detectable in MGUS patients further underlining that frequencies of naïve Treg cells increase rather early during tumor development and progression." (PMID 21904560, 2011).
tumor (continued). "We used TCR transgenic mice - one devoid of CD4 nTreg and the other with < 1% Foxp3 CD8s - whose tumor-infiltrating T cells and perhaps those in lymphoid organs of tumor-bearing mice would be engaged by cognate antigen, as well as being exposed to tumor-produced TGFβ." (PMID 22112546, 2011). "This newly defined fully functional CD4+CD127lowFOXP3+ Treg-cell population is expanded in all tumor entities as well as the premalignant MGUS supporting the hypothesis of increased Treg cells as a rather early event during tumor development." (PMID 21904560, 2011). "Furthermore, STAT6--a signal transducer downstream in the IL-13 receptor signaling pathway--is phosphorylated, suggesting the IL-13 from infiltrating CD4+ T cells in the tumor microenvironment may contribute to tumor development." (PMID 21281484, 2011). "Likewise, NK, NKT (type 1 NKT), and γδT cells are regarded as major sources of IFN-γ during the early phase of tumor development, whereas CD4+ and CD8+ T cells may become additional sources as adaptive immunity evolves." (PMID 21943203, 2011). "While the impact of antiretroviral therapy could not be evaluated because of limited published data, there are rare published cases in which the patients' tumor remained stable in size or regressed even with a modest CD4 response to highly active antiretroviral therapy (HAART)." (PMID 21437186, 2011). "Several recent studies have adopted the approach to use CD127, CD25, and FOXP3 for the quantification of Treg cells in tumor-bearing individuals and could demonstrate increased numbers of CD4+CD25highCD127low Treg cells in patients with solid tumors and hematologic malignancies." (PMID 21904560, 2011). "Additionally, we have detected some CD4− cells expressing FoxP3 in the tumor mass." (PMID 21559338, 2011). "Indeed different mechanisms of anti-tumor immunity may exist in mice treated with anti-CD4 versus anti-CD25." (PMID 22046294, 2011). "However, the role of pro-inflamatory CD4+ T-cells in the tumor control is still controversial." (PMID 20525350, 2010). "On the other hand, HLA-DR3tg mice, after immunization with Ad5.TRP-1, as performed in our study, might be a source of TRP-164–78-specific T cells, whose T cell receptors (TCR) could be cloned to generate TCR-recombinant tumor-reactive CD4+ T cells for adoptive therapy." (PMID 21152437, 2010). "Indeed, in several models, tumor immunosurveillance is augmented when CD4+CD25+ Tregs are depleted." (PMID 21234340, 2010). "The fact that most CD4+ T cells were also positive for Foxp3 shows that at different points of time during carcinogenesis in this model, an increasing number of phenotypical regulatory T cells (Tregs) were detectable at the tumor site demonstrating a potential protumoral effect." (PMID 20205946, 2010). "However, several mouse studies point to additional roles of CD4+ T cells in tumor control." (PMID 21152437, 2010). "Indeed, adoptive transfer of antigen-specific CD4+ T cells controlled tumor growth." (PMID 21048993, 2010). "Interestingly, removal of CD4+ T cells from the lymphocytes transferred from a large proportion of donor mice with tumors injected with PBS resulted in increased protection against the tumor challenge." (PMID 23087817, 2010). "In the present study, we reported that CpG-ODNs could enhance the antitumor efficacy of adoptive transfer of TILs into tumor-bearing nude mice which was accompanied by increased activation and proliferation in both CD4+ and CD8+ T cells, as well as the polarization of Th1 immune response." (PMID 20981279, 2010). "Interestingly, the entire phenomena could be reverted back by theaflavins that restore cytokine-dependent IL2Rγc/Jak-3/Stat-5A signaling in CD4+ T cells thereby protecting them from tumor-shed PGE2-induced apoptosis." (PMID 19812686, 2009). "Therefore, in order to establish itself, a growing tumor tries to overpower CD4+ T cells." (PMID 19812686, 2009).
tumor (continued). "Among these CD3+CD45+ TILs, we observed a decrease between the early/intermediate and the late time point in the proportion of TILs that were CD4+ (76.5% vs. 47.5%, P = 0.0003), suggesting that alternate T cell subsets may be infiltrating the tumor microenvironment, such as CD8+ CTLs or NK T cells." (PMID 19226468, 2009). "To investigate if depletion of T-regs could enhance the recognition of naturally processed epitopes in tumor cells by CD4 T cells, we compared DR-1-specific response between CD4+CD25+ T cells and CD4+CD25-T cells from the same donors in the IFN-γ ELISPOT assay." (PMID 19707583, 2009). "Moreover, IL-2 may affect different cell types, including CD4+ T cells, NK cells, macrophages and B cells, resulting in anti-tumour immunity." (PMID 19935800, 2009). "However, recent studies show that CD4 helper T cells, secreting IFNγ, may play an important role in tumour rejection as well." (PMID 18728665, 2008). "Human immunodeficiency virus (HIV)-associated KS (HIV-KS) is the most common tumour in HIV infection and it may occur at any level of CD4+ T cell count during HIV infection, but usually affects HIV-seropositive subjects with CD4+ T cell count below 200 cells/μl." (PMID 18226270, 2008). "In accordance with this hypothesis, patient 1 on our trial failed the first enrollment screening with less than 200 CD4+ cells/mm3, but was eligible following surgery when her CD4 cell count had recovered, indicating a possible immunosuppressive effect of the tumor." (PMID 17868452, 2007). "Although the generation and expansion of CD25+ CD4+ T cells may be a strategy to induce donor specific transplantation tolerance, it has been well documented in a mouse tumour model that CD25+ regulatory T cells suppress tumour specific responses, leading to tumour growth." (PMID 17711408, 2007). "However, CD4+ T cells have been implicated in the generation of effective anti-tumour memory CD8+ T cells; therefore we tested whether CD4+ T cells were critical to the maintenance of the immune response following PDT." (PMID 17505510, 2007). "Thus a supply of relevant cytokines for polarisation of the T-cell response in the direction of a general antitumour inflammatory response, giving rise to indirect killing by CD4+ cells in HLA class II-negative tumours may be part of the mechanism of action." (PMID 17060934, 2006). "Depletion of CD4+CD25+ TR cells using anti-CD25 mAb could promote anti-tumor immunity." (PMID 15679891, 2005). "Our observation suggests the CD4+CD25+/CD4+ proportion in spleen lymphocytes might be a sensitive index to evaluate the TR in tumor mouse models, and our results provide some information on strategies of antitumor immunotherapy targeting CD4+CD25+ regulatory T lymphocytes." (PMID 15679891, 2005). "Therefore, DC harvested after physical activation and overnight culture could expand CD4 T cells and potentially provide the help required for licensing of anti-tumor CD8 T cell responses." (PMID 16029505, 2005). "Conversely, an increased percentage of CD4+CD25+ TR cells in total CD4+ T cells was found in peripheral blood of cancer patients and depletion of CD25+ cells alone or combination with other strategies might cause tumor regression." (PMID 15679891, 2005). "However, it seems that the presence of a tumour will eventually induce CD4+ T-cell immunity." (PMID 15986031, 2005). "In order to assess the expression of DCN in tumour cells, stroma and immune cells, SPTCs from 27 patients were stained with a 6‐plex immunofluorescent panel including DCN, CD4, CD8, CD20, CD68, and PanCK." (PMID 41392017, 2026). "LASSO regression screened out 10 key prognostic factors: aspartate aminotransferase, total bilirubin, albumin (ALB), white blood cell count, DD, alpha-fetoprotein, CD4+ T cell count, PVTT, tumor number (≥3) and lymph node invasion." (PMID 42109683, 2026).
tumor (continued). "Intracellular cytokine staining revealed that, compared with healthy lymph nodes, EBL tumor-affected lymph nodes showed increased proportions of CCL4 expressing cells, particularly among CD4+ T cells and B cells." (PMID 42158858, 2026). "The correlation analysis and the immunological and clinical outcomes of rBCG immunotherapy underscores the pivotal role of orchestrated interactions between CD4+ T cells, CD8+ T cells, and dendritic cells in shaping the tumor microenvironment." (PMID 41522339, 2026). "We applied multiplex immunofluorescence to pre-treatment tumor samples from 11 patients with advanced BTC, staining for CD4, CD8, CD20, and CD163 to identify T cells, B cells, and macrophages." (PMID 42293570, 2026). "The top ten differentially expressed proteins in patient clusters 1 and 2 showed an upregulation in the tumor periphery and included CD3, CD20, CD8, CD45, PD-1, fibronectin, SMA, CD56, CD4 and BCL6." (PMID 41545625, 2026). "Flow cytometry analysis demonstrated increased infiltration of CD4+ T cells, CD8+ T cells, and NK cells in the tumor tissues of the mCGYL-LOx treatment group, accompanied by a significant reduction in Tregs." (PMID 41424843, 2026). "In peripheral blood, mice exhibiting higher activation of CD4+ and CD8+ T cells displayed significantly smaller tumor volumes, establishing a strong inverse correlation between T cell activation and tumor growth." (PMID 41522339, 2026). "Combination therapy significantly increases lipid peroxidation in tumor cells, elevates the levels of IFN‐γ, TNF‐β, CD8+ T, and CD4+ T cells, and enhances the anti‐tumor action of immune cells." (PMID 41560416, 2026). "Our flow cytometric analysis showed differential expression of IL7R, CD40L, PD1, ICOS and HLA-DR between tumor Tfh-like subsets defined based on CD49f and CD103 expression within the CD4+ gate." (PMID 41542042, 2026). "CD8+ T cells primarily eliminate tumor cells by recognizing specific antigens and class I MHC molecules, while CD4+ T cells activate other immune cells." (PMID 41158754, 2026). "Functionally, JQ1 markedly improved tumor recognition by autologous MART-1- and neoantigen-specific CD8+ TIL, while dampening CD4+ TIL activation through the downregulation of Cathepsin S (CTSS)." (PMID 42057381, 2026). "There was insufficient tumor remaining from d1 of Patient#1; so values for CD8, CD4, and FoxP3 infiltrates from the single‐color IHC were used as baseline values for this patient." (PMID 41514118, 2026). "Tumor-infiltrating lymphocytes (TILs), particularly CD8+ cytotoxic T-cells and CD4+ helper subsets, are central to tumor immunosurveillance and correlate with improved outcomes." (PMID 41562715, 2026). "Together, these results demonstrate that the tumor microenvironment itself harbors phenotypically distinct immune cell populations, with 4T1 tumors promoting a RANKL+ CD3+ CD4+ T cell phenotype and 67NR tumors sustaining OPG+ CD19+ B cells." (PMID 41364090, 2026). "Lifileucel (LN‐144) is an autologous TILs therapy that uses TILs from patient's tumor‐tissue and being expanded ex vivo to produce polyclonal patient‐specific TILs (mix of CD8+ and CD4+ T cells)." (PMID 41492362, 2026). "CD4 depletion also abolished an increase in the effector CD8+ T cells in DLN and total and MC38 (AdpgkMUT)-specific CD8+ T cells in tumor by Bpmel-OVAI-Ea cell adjuvant therapy." (PMID 41348109, 2026). "Comparative analysis revealed that tumors with high A3C expression exhibited significantly greater infiltration of anti-tumor effector cells, including CD8+ T cells, resting CD4+ memory T cells, and monocytes." (PMID 41514678, 2026). "Integrated scTCR-seq analysis revealed enhanced clonal expansion of tumor-reactive CD8+ T-cell subsets and reduced the frequency of CD4+ Treg-Ctla4 under combination therapy." (PMID 41673717, 2026).